CDKN2A (cyclin dependent kinase inhibitor 2A)
Diseases named in the same sentence as CDKN2A in open-access papers (continued):
Sharing a sentence is not in itself a finding about the gene and the disease.
tumor (continued). "A correlation between breastfeeding and methylation of a cancer-related gene, CDKN2A, in tumour tissues among premenopausal but not postmenopausal women was observed in the final paper." (PMID 30096154, 2018). "Subsequent RNA-seq and western blot revealed that the expression of HIF1ɑ was closely correlated with HIF1A duplication in tumor tissues, whereas gene expression of CDKN2A and PALB2 was not significantly changed (fold-change < 2)." (PMID 30062063, 2018). "This resemblance is not due to the activation of programs common to most cancer cells because the Vav1−/− tumor gene signature does not overlap with the transcriptome of tumor T cells obtained from mice defective in tumor suppressors such as Pten and Cdkn2a." (PMID 29136506, 2017). "In contrast to CDH1, cases positive for methylation of CDKN2A promoter in tumor tissues were much less even in long-DM (30%) and in non-DM (10%)." (PMID 29273724, 2017). "CSMD1, CDKN2A, NOTCH1, and SMAD4 are known to be tumor-suppressor genes." (PMID 29340043, 2017). "Age, gender, BMI, tumor size, tumor stage, glycated hemoglobin levels and CDKN2A promoter methylation did not affect the outcome." (PMID 29273724, 2017). "In consideration of tumor heterogeneity, we have not found KRAS, CDKN2A or SMAD4 mutations in our samples." (PMID 28008139, 2017). "Similarly, in many cancers, the transcription of cyclin-dependent kinase inhibitor 2A (CDKN2A), an important tumor suppressor gene, has been found to be terminated after the chromatin blocking of its promoter region." (PMID 28302063, 2017). "Methylation levels of CDKN2A exon 2 in tumor tissues and also in tumor-distant tissues showed a weak but significant negative correlation with the proliferative activity of the tumor (r = −0.485, p = 0.041 and r = −0.498, p = 0.036, respectively)." (PMID 28403857, 2017). "In general, we see no reason to presume that the driver of a tumor CNA (in this case CDKN2A) is necessarily also the driver of the immune effect." (PMID 28749946, 2017). "Furthermore, STAT3 acetylation but not tyrosine phosphorylation has been shown to be required to silence expression of many tumor suppressor genes such as SHP-1, CDKN2A by recruiting DNMT1 to methylate their promoter in cancer cells." (PMID 29126425, 2017). "Using hierarchical clustering, 43 primary tumor samples from patients treated at MMC were clustered by the methylation array data for four CpGs within the downstream nonpromoter region of CDKN2A." (PMID 28102032, 2017). "In addition, another lncRNA located in the CDKN2A intron, RP11-149I2.4, was also 6.6 times (P<0.05) upregulated in HPV16+ tumours compared with HPV− tumours." (PMID 29263803, 2016). "Interestingly, some upregulated genes, such as Myb, Rbl2 and Cyclin-dependent kinase inhibitor 2A (CDKN2A; fold change: 2), code for proteins able to act as tumor suppressors." (PMID 27876093, 2016). "We did not see upregulation of reported tumour-suppressor genes, such as CDKN2A, CDKN2B and PML, and factors for neuronal differentiation, such as SMARCC1 and DLX2, in our microarray analysis." (PMID 26838672, 2016).
tumor (continued). "The genes CDKN2A, CDKN2B, and RB1 function as tumor suppressors; their decreased expression occurs via several mechanisms, including methylation, and contributes to the development of neoplasias." (PMID 26317630, 2015). "Eleven cancer related genes were found to have methylation (defined as more than 10 % methylation) in at least some of the tumours: RASSF1A (64 %), TWIST1 (61 %), CDH13 (51 %), APC (50 %), MAL (35 %), GSTP1 (30 %), WIF1 (26 %), RARβ (19 %), BRCA1 (2 %), CDKN2A (2 %) and TP73 (2 %)." (PMID 26452468, 2015). "The epigenetic changes found in the tumor area did not correlate with clinicopathological features except CDKN2A methylation, which was correlated with better prognosis." (PMID 24782031, 2014). "The aim of this study was to describe the morphological characteristics and the DNA methylation status of the CDKN2A,CDH1, ATM, FHIT and RAR- genes in the central and peripheral part of the tumor and the surgical margin and evaluate their prognostic significance." (PMID 24782031, 2014). "These genes that were only identified by one platform included well known tumor suppressors such as CDKN2A and RASSF5 that obviously warrant investigation, but did not meet the criteria for this specific study." (PMID 24454902, 2014). "They detected 24 bp deletion within exon 1 of CDKN2A in 12% of the tumours which did not correlate with pathological parameters or cancer specific survival." (PMID 24877109, 2014). "Also, changes in tumour suppressor gene-related regions, such as 9p21.3 (CDKN2A) 9p23-24.1 (PTPRD), 13q14.2 (RB1), were significantly fewer in tumours with ALK fusion." (PMID 23289484, 2013). "Both CDKN2A and CDKN2B function as cell cycle regulators and tumor suppressors." (PMID 24330828, 2013). "Although earlier reports did not identify a correlation between CDKN2A methylation and tumor volume, invasiveness, recurrence, or malignancy, more recent studies have associated CDKN2A methylation with tumor volume, grade, and patient age." (PMID 24367530, 2013). "Homozygous deletion was seen only at 9p21.3 including CDKN2A and limited to EGFR-mutated tumours among ALK fusion-negative neoplasms as reported in the literature and also seen in ALK-fusion positive ones." (PMID 23289484, 2013). "Taken together, these observations suggest that MTAP functions as a tumor suppressor gene independent of CDKN2A/ARF." (PMID 23840755, 2013). "CDKN2A methylation positivity was associated with MSI (p = 0.025), BRAF mutation (p < 0.0001), higher tumor grade (p < 0.0001), mucinous histology (p = 0.0209) but not with KRAS mutation." (PMID 22925370, 2012). "The aim of this study is to evaluate site-specific CDKN2A methylation patterns in both tumor and matched non-neoplastic tissues, amplification conditions and to propose a threshold value for CDKN2A methylation “positivity” by pyrosequencing." (PMID 22925370, 2012). "Next, to examine whether CCND1 and CDKN2A could be utilized as an RB1 classifier in vivo, the RB1 status was determined in xenograft tumor samples." (PMID 21447152, 2011). "All but one (HCC patient No. 21) corresponding non-tumor samples obtained from patients with HCC were found to have an unmethylated CDKN2A promoter." (PMID 20569442, 2010). "Interestingly, the CpG sites with strongest ability to discriminate tumor from surrounding tissue were found in the promoter of genes hypermethylated in HCC samples (e.g. APC, RASSF1A, CDKN2A, and FZD7)." (PMID 20305825, 2010).
tumor (continued). "In common with other cancers, WTs also show tumour suppressor gene silencing which includes genes such as HACE1 (73% of tumours analysed), RASSF1 (56%), CASP8 (43%), MGMT (30%), RASSF5/NORE1 (15%), and CDKN2A (10–15%)." (PMID 19956686, 2009). "Cyclin-dependent kinase inhibitor 2A (p16) and MCM7 were significantly upregulated in one of the tumour subsets, indicating that this subset (Gr2) could be characterised by E2F-regulated transcription." (PMID 18349847, 2008). "Not only have known tumor suppressor genes like Cdkn2a (p16), Itga4 (α 4-integrin), and Igfbp7 been identified as targets of aberrant methylation in cancer by RLGS, but also novel tumor suppressor genes such as TCF21, SLC5A8, ID4, BMP3B, and SOCS1 have been identified by RLGS." (PMID 18053125, 2007). "Detailed statistical analysis showed that in both triplets, LOH in MLH1 correlates with lower, and in CDKN2A with higher grading (P<0.01, ANOVA), but LOH in TSG on 8p22 and RB1 gene are not directly linked to tumour grading." (PMID 15083191, 2004). "They suggested that CDKN2A inactivation was an in vivo genetic event contributing to tumour biology rather than an in vitro phenomenon." (PMID 15305192, 2004). "Interestingly, the heterogeneous region in the left liver lobe of Oncopig 2 also harbored PTEN and CDKN2A gene edits, suggesting the development of a diffuse, undefined lesion rather than a well-defined tumor at this injection site." (PMID 39780710, 2025). "The authors concluded that the non-negligible CDKN2a methylation in matching mucosa may confound the assessment of tumor-specific hypermethylation, suggesting that matching mucosa should be used as a control." (PMID 40357388, 2025). "One possibility is that different cellular clones within the same tumour may carry distinct genetic and/or epigenetic alterations, which could result in variable MTAP expression—an observation that mirrors the heterogeneity noted in CDKN2A deletions by FISH." (PMID 40566743, 2025). "However, samples equipped with CDKN2A mutation presented no CDKN2B mutation, indicating the independency between the mutation pattern of these two tumor suppressor genes." (PMID 39844467, 2025). "Using an immune-competent model of de novo MPNSTs, developed through the Cas9-mediated inactivation of Nf1 and Cdkn2a, we found that the combination of CDK4/6 and MEK inhibitors uniquely induced transient tumor regression, a phenotype not seen in immune-deficient preclinical models." (PMID 40723291, 2025).
tumor (continued). "Both the white blood cell count and the proportion of peripheral blood immature cells at diagnosis were greater in the CDKN2A/B deletion group than in the non-deletion group, suggesting that pediatric patients with CDKN2A/B deletion had a greater tumor burden at diagnosis." (PMID 40017529, 2025). "Moreover, 12 cases with high, but not complete, MTAP expression (50%–99% of positive tumour cells) were also found; among them, six cases (50%) harboured a CDKN2A HD, notwithstanding preserved MTAP expression." (PMID 40566743, 2025). "However, the biopsy from the tumor in Oncopig 1 did not harbor PTEN or CDKN2A gene edits, possibly owing to sampling bias of the heterogeneous mass, which showed KRASG12D IHC staining in a different biopsy from the same mass." (PMID 39780710, 2025). "However, our results point to TRIM24::NTRK2 not being the only driver in this tumor, but is likely a combination with CDKN2A/B HD, pTERT, and other acquired alterations in later relapses." (PMID 41331048, 2025). "Furthermore, tumours with high mitotic counts frequently, but not predictably, show CDKN2A/B deletions, which is relevant for accurate grading." (PMID 40356449, 2025). "Using proteomics, we showed that the NF2−/− tumours divided into two distinct groups with distinct underlying mutational spectrum, NF2 clusters 1 and 2, independent of NF2 severity score, chromosome loss, CDKN2A/B and TERT mutations." (PMID 40562609, 2025). "A recent report has documented that cyclin dependent kinase inhibitor 2A (CDKN2A) in GBM governs the sequestration of oxidizable PUFAs into triacylglycerides (TAGs) within lipid droplets and alters the acyl tail composition in fatty acids, enabling tumor cells more tolerant to lipid peroxidation." (PMID 39309434, 2024). "However, the relationship between CDKN2A loss and the epithelial‐mesenchymal transition (EMT) process in tumour cells has not been reported." (PMID 38279519, 2024). "Moreover, SMURF and Nano-GLADIATOR do not account for tumor fraction and are unable to distinguish between homozygous and hemizygous deletions at the CDKN2A/B locus." (PMID 38736685, 2024). "Through both univariable and multivariable analyses, we also revealed that high CDKN2A and SMAD4 mutation abundances in ctDNA but not in tumor and high ARID1A mutation abundances in both ctDNA and tumor at baseline and/or the second measurement were linked to inferior OS and/or PFS." (PMID 38378604, 2024). "In the non-tumor area, we identified nearby spots classified as CDKN2A+, CDKN2A-, neither, or both." (PMID 38888512, 2024). "Therefore, we hypothesized that regulating IGF1, CDKN2A, BIRC5, and SPP1 levels may affect the tumor immune microenvironment in HCC." (PMID 39042294, 2024). "However, no signal transmission was observed between the tumor spot CDKN2A- and nearby CDKN2A- cells in these signals." (PMID 38888512, 2024). "Resistance to treatment may be due to heightened cyclin E1–CDK2 and PI3K–mTOR signaling in tumor cells lacking CDKN2A, which suggests that other changes can reduce the effectiveness of CDK4/6 inhibitors." (PMID 38534309, 2024). "Importantly, in both the bulk and single-cell data increased HOX expression of those present in C2 was not restricted to tumours with CDKN2A/B HD." (PMID 39382765, 2024). "Considering that CDKN2A is differentially expressed in SCLC and may play an important role, this study further analyzed the expression and clinical significance of CDKN2A in a number of tumor types." (PMID 38206516, 2024). "Considering that CDKN2A was differentially expressed in SCLC and might play an important role, this study further analyzed the expression and potential molecular mechanism of CDKN2A in a number of tumor types." (PMID 38206516, 2024).
tumor (continued). "Moreover, many unique mutations were only found in CSF samples, but not in the tumor tissue and plasma samples, which includes FH mutation, SETD2 mutation, WT1 mutation, CDKN2A mutation, CDKN2B mutation." (PMID 36937524, 2023). "Thus, we speculated that CDKN2A rs3088440 might up-regulate the expression of PD-L1 through CDK4, hence inducing CD8+ T lymphocytes depletion and ultimately leading to tumor cell proliferation and metastasis." (PMID 37314514, 2023). "Despite the clear advantages of a de novo tumor in an immunocompetent environment, the tumor remains a mouse tumor and not a human tumor—and these may act/react differently, e.g. CDKN2A/B is present at chromosome 9 in humans but chromosome 4 in mice." (PMID 37898750, 2023). "The differential expression of CDKN2A was firstly assessed using the TIMER2 repository and the output revealed that except for PAAD and PCPG, all of the analyzed tumors with normal tissue for comparison exhibited a significant upregulation of CDKN2A in tumor tissue versus control." (PMID 37626750, 2023). "Many of the most frequent actionable alterations within TMB-H tumors were within tumor suppressor pathways (PIK3CA/PTEN, CDKN2A, BRCA1/2, NF1, ATM, and TSC1/2), suggesting that many variants may be passenger rather than driver alterations in the setting of highly altered tumors." (PMID 36602798, 2023). "Additionally, the correlation between CDKN2A and the components of the immune system under tumor conditions is still not fully described." (PMID 37626750, 2023). "However, the tumor suppression mechanism of CDKN2A from a cuproptosis perspective had not been investigated, which is worthy of studying." (PMID 37041979, 2023). "Ex vivo expansion of GEMM-derived EHE tumours with wild-type Cdkn2a was not possible." (PMID 37296967, 2023). "CDKN2A heterozygous deletion was observed in many tumor types without any prognostic impact." (PMID 36900302, 2023). "We applied a multivariable analysis to investigate whether CDKN2A could serve as a predictive biomarker independent of clinical and tumor characteristics." (PMID 35739333, 2022). "In addition, the LOH of CDKN2A, a critical tumor suppressor gene and senescence effector, occurred in one subline of TERT-NHUCs, while its promoter hypermethylation was more frequent and led to silent CDKN2A expression." (PMID 36713366, 2022). "In addition, CDKN2A (p = 2e-24), DLAT (p = 8.8e-09), DLST(p = 0.00047), GLS(p = 2.5e-13) and PDHA1 (p = 8.3e-14) were significantly different at the in HCC patients with high tumor grades, low tumor grades and adjacent normal tissues." (PMID 36588699, 2022).